YAP1 (Yes1 associated transcriptional regulator)
Diseases named in the same sentence as YAP1 in open-access papers (continued):
Sharing a sentence is not in itself a finding about the gene and the disease.
tumor (continued). "Here, the authors show that the long coding RNA, LcnBRM, regulates the self-renewal of liver CSCs and tumour initiation through binding to BAF complex thereby activating YAP1." (PMID 27905400, 2016). "Hh signaling inhibition reduces Yap1 expression, and Yap1 knockdown significantly inhibits tumor progression." (PMID 27685633, 2016). "As a transcriptional coactivator, YAP1 is the downstream effector of the Hippo signaling pathway which is an essential regulator of organ size and tumor growth by modulating cell proliferation and apoptosis." (PMID 26716514, 2016). "Yap1, a potent oncogene expressed in both human and mouse tumor tissues, is amplified in various cancers." (PMID 27685633, 2016). "In normal haematological cells, YAP1 forms a complex with the tumour p73 to support the transcription of proapoptotic genes, such as BAX and PIG3 expression." (PMID 27042197, 2016). "In many cell types, the activity of Yap1 is regulated by a tumor-suppressive pathway called the Hippo (Hpo) signaling pathway." (PMID 27000077, 2016). "Pediatric patients with ACT who experienced tumor recurrence and/or metastasis and those who died presented increased YAP1 mRNA expression in tumor tissues." (PMID 27705928, 2016). "About half of the tumor specimens stained positive for nuclear YAP1, which is the functionally active form of YAP1." (PMID 26716514, 2016). "Since it regulates tumor cell proliferation and apoptosis, YAP1 has been described as a candidate oncogene." (PMID 27325246, 2016). "Altogether, lncBRM-mediated YAP1 signalling is required for the self-renewal of liver CSCs and tumour propagation." (PMID 27905400, 2016). "In summary, lncBRM is highly expressed in HCC tumours and liver CSCs, which triggers YAP1 signalling to promote self-renewal of liver CSCs and initiate tumour propagation." (PMID 27905400, 2016). "Several studies have reported increased expression of Nodal and YAP1 in many tumor types, including melanoma, liver cancer, breast cancer, ovarian cancer, and glioma." (PMID 27325246, 2016). "The tumor volume and tumor weight in the YAP1 shRNA BGC-823 group was smaller than those in the BGC-823 group (both P < 0.05)." (PMID 27835600, 2016). "As a result, we estimated that there was at least one tumor initiating event from 714 Yap1-flp tumor cells (TIC frequency of 1/714)." (PMID 26695440, 2016). "Consistently, although YAP1 expression was higher in tumours and highest in the Δp/np organs, phosphorylation on the Hippo target site S127 was not significantly altered." (PMID 28000790, 2016). "As coactivators, YAP1 or TAZ interacts with the TEAD/TEF family of transcription factors (TEAD1-4) to transcriptionally regulate the target genes in tumor tissue." (PMID 26885617, 2016). "Yap1 has been demonstrated to promote tumor growth, progression and metastasis in many solid tumors." (PMID 26695440, 2016). "By comparison, the tumor initiating events in tumors with active Yap1 were 4 times higher (p< 0.01)." (PMID 26695440, 2016). "The genomic instability of the miR-34a-high tumor cell line was reflected in high-copy amplicons coding for the oncogenes Yap1, Birc2, Birc3, Dcun1d5 (all on 9A1) or the leptin receptor (4C6)." (PMID 26871287, 2016). "Compared with TICs from the Yap1-flp tumor, Yap1 expression in the nucleus of TICs from Yap1-ko tumors was dramatically lower." (PMID 26695440, 2016). "Yes-associated protein 1 (YAP1) is an effector of Hippo pathway, which is critical for regulating organ size, cell proliferation and tumor growth in mammals." (PMID 26263504, 2015). "More specifically, YAP1 expression was elevated in the tumor and low in the adjacent normal crypts, whereas the opposite was true for NDR2." (PMID 25601544, 2015). "By linking enhancers to genes, we provide a list of novel YAP1 target genes in an oncogenic setting that we show can readily be exploited in tumor classification and provides a foundation for further investigations." (PMID 26295846, 2015).
tumor (continued). "In human tumors, failure to activate LATS1 due to either GNAQ mutations in uveal melanoma or through inactivation of NF2/merlin in the tumor-prone neurofibromatosis syndrome prevent this inhibitory signal and make YAP1 permissive for activation." (PMID 26549256, 2015). "Restriction of YAP1 transcriptional activity is the principal mechanism of growth and tumor suppression by the Hippo pathway." (PMID 26263504, 2015). "The YAP1 characters above benefit the growth of tumor cells and are bad for prognosis in many malignancies." (PMID 26263504, 2015). "NDR kinases function as tumor suppressors in the intestinal epithelium by negatively regulating YAP1." (PMID 25601544, 2015). "In recent years, plenty of studies have been carried out to explore how YAP1 effects, especially on tumorigenesis, tumor development and cancer prognosis." (PMID 26263504, 2015). "Resultant tumors have high Yap1 expression, which is significantly reduced with Hh inhibition, and suppression of Yap1 blocks tumor progression." (PMID 26389076, 2015). "show that the clinical phenotype is driven by both RASSF1A loss and the independently transcribed RASSF1C isoform, which promotes SRC activation, pseudo-EMT, and β-catenin/YAP1-dependent invasion of tumor cells." (PMID 26549256, 2015). "YAP1, a transcriptional co-activator, is inhibited by the Hippo tumor suppressor signaling pathway and regulates multiple cellular processes by activating several transcription factors, such as TEAD1-4." (PMID 25473897, 2015). "RASSF1A is a hippo pathway scaffold that switches YAP1 association from oncogenic TEAD transcriptional complexes to tumor-suppressive YAP1/p73." (PMID 26549256, 2015). "In fact, YAP1 has been reported to exhibit both oncogenic properties and tumor-suppressive functions in distinct in vitro or in vivo models." (PMID 24810989, 2014). "In the gene expression dataset, YAP1 mRNA quartiles were positively correlated to tumour size in the ER- subgroup (p = 0.037)." (PMID 24559095, 2014). "As correlations in the screening and randomised patient cohorts implied that YAP1 behaves differently depending on the tumours’ expression of ER, recurrence-free survival was analysed in ER+ and ER- subgroups of the gene expression dataset." (PMID 24559095, 2014). "Depletion of SOCS5/6 or upregulation of YAP1 can bypass the requirement for oncogenic Ras in anchorage independent growth in vitro and tumor formation in vivo." (PMID 25180228, 2014). "Active migration of tumor cells is a prerequisite for tumor cell invasion and for metastasis development and our gene expression analyses indicated that YAP1 modulates several target genes that are reported to control cell-cell contact and cell migration." (PMID 24810989, 2014). "Initially, YAP1 was classified as a tumor suppressor gene (or at least as helper of tumor suppressors), as it was reported to exert pro-apoptotic functions." (PMID 24810989, 2014). "We screened a panel of human tumor samples and cancer cell lines and identified that the YAP1 amplification event is actually present in up to 23% of the cases." (PMID 24810989, 2014). "Notably, low YAP1 mRNA was independently associated with decreased recurrence-free survival in the gene expression dataset, specifically for the luminal A subgroup (p < 0.001) which includes low proliferating tumours of lower grade, usually associated with a good prognosis." (PMID 24559095, 2014). "Quartiles 2, 3 and 4 were in the bottom of the graph whereas quartile 1 (holding the tumours of lowest YAP1 mRNA expression) demonstrated a remarkably better outcome after 5 years of follow-up, although the trend was not persistent." (PMID 24559095, 2014). "ER+ patients with tumours of YAP1 expression scored as either weak, intermediate or strong (score 1-3) did significantly better when treated with tamoxifen compared to no treatment." (PMID 24559095, 2014).
tumor (continued). "Low YAP1 mRNA expression was correlated to a decreased recurrence-free survival and YAP1 mRNA proved to be an independent prognostic factor after adjustment for known prognostic factors such as grade, tumour size and lymph node involvement." (PMID 24559095, 2014). "Literature data report apparently discrepant results on the carcinogenic role of YAP1, which acts either as oncogene or as tumor suppressor in different in vitro and in vivo models." (PMID 24810989, 2014). "Literature data report that chromosome region 11q22, containing YAP1 gene, is amplified in a small percentage of samples from multiple human tumor types." (PMID 24810989, 2014). "In our immunostaining studies, YAP1 staining is generally more intense in the cytoplasm than in the nucleus, and the tumor has a significantly higher proportion of cells with positive YAP1 staining in the nucleus than the adjacent normal (77% vs. 48%)." (PMID 22396793, 2012). "Approximately 77% (49/64) of the PDA cases had positive (scored 1+ or higher) nuclear YAP1 staining in tumor cells, 63% (31/49) of which had moderate (2+) or strong (3+) staining." (PMID 22396793, 2012). "Negative regulator of oncoprotein YAP1 in the Hippo signaling pathway plays a pivotal role in organ size control and tumor suppression by restricting proliferation and promoting apoptosis." (PMID 22909338, 2012). "Although a significant percentage of adjacent normal cases stained positive for YAP1, the overall expression level is significantly higher in the tumor." (PMID 22396793, 2012). "On the other hand, when cells undergo proliferation, YAP1 translocates to the nucleus to associate with TEAD family transcription factors, implicated in tumor growth and metastasis." (PMID 22558212, 2012). "Furthermore, simvastatin is reported to inhibit tumor growth by repressing the activation of RhoA GTPase and nuclear translocation of YAP1." (PMID 41513610, 2026). "Higher tumor stiffness correlates with nuclear YAP1 accumulation." (PMID 41596432, 2026). "β‐Catenin and Yap1 collaborate to propel tumor progression in hepatoblastoma." (PMID 40066231, 2025). "Additionally, our results showed that YAP1-positive cells were mainly distributed in the tumor stroma of SCLC, consistent with previous research findings." (PMID 40051494, 2025). "Mechanistically, the NF-κB–TGF-β1–YAP1 axis has been implicated in both the establishment and homeostatic maintenance of the myCAF state; co-inhibition of TGF-β1 and YAP1 partially reverses myCAF activation and increases tumor-cell sensitivity to enzalutamide (ENZ)." (PMID 41514658, 2025). "Future research should leverage advanced genomic, epigenomic, and single-cell transcriptomic approaches to determine whether YAP1-driven tumors constitute a true molecular subtype or merely reflect a transient state influenced by tumor plasticity." (PMID 40333678, 2025). "In contrast, STK3 deletion led to the decreased activity of the oncogenic YAP1 signaling, which might result from its significant inhibition on the tumor cell malignancy." (PMID 40604818, 2025). "Overactivation of the YAP1–Nr4a1 pathway could promote tumor growth, whereas moderate activation may facilitate the restoration of aging neurons." (PMID 40468463, 2025). "Meanwhile, FAK and YAP1 are frequently co‐dysregulated in the CRC patient population and appear associated with disease progression, consistent with their roles in intestinal regeneration, tumor development, and disease recurrence." (PMID 40959971, 2025). "Importantly, Abemaciclib not only markedly suppresses cell proliferation in vitro but also inhibits tumor growth and enhances chemosensitivity in vivo, which are largely reversed by reconstituting YAP1 expression." (PMID 40307228, 2025). "We also examined the TGFβ3/GLI2/YAP1 (the TGY signature) expressions in the tumor samples." (PMID 40027190, 2025).
tumor (continued). "The direct PIEZO1-Src-YAP1 axis suggests a rapid, potentially Hippo-independent pathway that may prioritize immediate proliferative or survival responses in a tumor setting." (PMID 40977060, 2025). "Targeting KDELR1 may enhance the efficacy of CHT and inhibit tumour progression by restoring the tumour suppressor activity of the Hippo-YAP1 pathway." (PMID 41294677, 2025). "Regarding the relationship of miR-375-5p with MTC, different mechanisms have been proposed to explain its influence on MTC prognosis, including the downregulation of YAP1, which promotes tumor progression, and dysregulation of the phosphatidylinositol 3-kinase (PI3K)/Akt signaling pathway." (PMID 40002224, 2025). "Importantly, the critical role of the axis in tumor cell proliferation, cell cycle progression, and survival, phenotypic plasticity, and chemoresistance is intrinsically tied to activation of YAP1 and the BRD4‐MYC axis." (PMID 40959971, 2025). "Taken together, our findings reveal the previously unrecognized tumor-promoting function of CDK4/6-DUB3 axis through stabilizing YAP1, providing preclinical evidence that targeting this axis may represent a promising therapeutic strategy for HCC." (PMID 40307228, 2025). "However, pathological overactivation of YAP1/TAZ resulting from Hippo dysregulation is a hallmark of many cancers, promoting tumor initiation, invasive behavior, metastasis, and resistance to therapeutics." (PMID 41009501, 2025). "Moreover, confirming the presence of WWTR1::CAMTA1 or YAP1::TFE3 gene fusion in the tumor would offer more convincing evidence." (PMID 40040722, 2025). "YAP1-mediated regulation may contribute to the suppression of immune activation, which, in turn, impacts the anti-tumor response to chemotherapy." (PMID 40918140, 2025). "Consistent with our speculation, upregulation of YAP1 increased the short- and long-term viability of tumor cells under DDP treatment." (PMID 40191726, 2025). "The strong association between pre-treatment YAP1 expression and HER-2-positive subtype in our study further supports its relevance as both a biomarker of response and a candidate for molecular targeting, particularly in aggressive tumor types." (PMID 40731926, 2025). "Inhibiting CSN6 or enhancing SPOP activity could promote HMGCS1 degradation, thereby diminishing YAP1 activation and subsequent tumor growth." (PMID 40521202, 2025). "Further investigation revealed pronounced upregulation of YAP1 in tumor tissues." (PMID 39523731, 2025). "Further experiments aimed at restoration corroborated that the suppressive impact of CMD‐BHQ3‐PTL/DOX@RBCm on stemness in SW480 and LoVo tumor cells could be counteracted by stable transfection of YAP1 via lentivirus overexpression." (PMID 39523731, 2025). "Importantly, the combination of verteporfin and DDP not only enhanced the immune response but also reduced immune exhaustion in the tumor microenvironment, indicating YAP1 as a therapeutic target to overcome immune suppression during chemotherapy." (PMID 40918140, 2025). "In our research, the regulatory function of mechanic-m6A on YAP1 was identified in response to the PDAC heterogeneous stiffness, in which local stiff niches enhance YAP1 levels to boost the tumor cell stem-like type via METTL14/IGF2BP3-suppressed YAP1 mRNA decay." (PMID 40822927, 2025). "Our findings suggest that targeting the piR-31115/METTL3/YAP1/IGF2BP2 signalling pathway may offer a promising strategy for inhibiting tumour angiogenesis in TNBC." (PMID 39820521, 2025). "Importantly, this tumor growth inhibition was largely abrogated by the reconstitution of YAP1 expression." (PMID 40307228, 2025). "Notably, the triple combination of oHSV, RTx, and IGF1R blockade yielded synergistic anti-tumor effects, abolished YAP1 expression, and significantly enhanced survival in orthotopic BC and GBM models." (PMID 41510300, 2025).
tumor (continued). "Furthermore, in the tumor parenchyma, both the proportion and the cell density of YAP1-positive cells are positively correlated with that of FOXP3-positive cells." (PMID 40051494, 2025). "Indeed, IGF1R blockade suppressed IGF1R signaling and YAP1 expression in a dose-dependent manner, suppressing tumor cell proliferation, self-renewal, and enhancing survival in orthotopic GBM and BC models." (PMID 41510300, 2025). "The interplay between YAP1 and tumor immunology reveals complex, and at times contrasting, mechanisms that may either support or inhibit antitumor immunity, presenting both challenges and opportunities for therapeutic intervention." (PMID 40977060, 2025). "Hence, the potential involvements of other substrates of CDK4/6 besides YAP1 in tumor progression of HCC need to be further investigated." (PMID 40307228, 2025). "Notably, the cell density of YAP1-positive cells in the tumor stroma was significantly correlated with OS (r = -0.552, P = 0.040)." (PMID 40051494, 2025). "Notably, we demonstrated that the inhibitory effects of abemaciclib on YAP1 stability and YAP1‐driven tumor progression are largely mediated by DUB3, a previously unidentified deubiqutinase of YAP1 in CRC." (PMID 39968498, 2025). "Additionally, the level of YAP1 level was positively correlated with the N stage (N1 vs N0, p < 0.05), G histologic stage (G3 vs G1, p < 0.05), and R residual tumor state (R1 vs R0, p < 0.05)." (PMID 40822927, 2025). "Moreover, our study favors a potential collaboration between FAK and YAP1 in the promotion of tumor metastasis in CRC." (PMID 40959971, 2025). "In contrast, YAP1 knockdown in CAFs weakened these pro-tumor effects." (PMID 41514658, 2025). "Notably, the percentage of the samples that enriched of YAP1 was increasing in posttreatment tumour samples than pretreatment (P = 0.04, chi-squared test)." (PMID 41290592, 2025). "Furthermore, treatment with Abemaciclib markedly mitigated YAP1 protein levels and exhibited a substantial tumor-suppressive effect in HCC cells reconstituted with DUB3 WT." (PMID 40307228, 2025). "Overall, the available evidence suggests that μg, through the inhibition of adhesion and growth pathways (e.g., FAK, RhoA, YAP1, Cyclin D), cytoskeletal remodeling, and modulation of apoptosis/survival regulators, exerts a time- and cell type-dependent suppressive effect on tumor proliferation." (PMID 40940834, 2025). "Recent studies have highlighted the involvement of STUB1 in various human malignancies, as it regulates the stability and activity of several tumor-associated transcription factors, such as CRIP1, YAP1, HIF-1α, and c-Myc, thereby influencing tumor growth, invasion, metastasis, and angiogenesis." (PMID 40859326, 2025). "CMD‐BHQ3‐PTL/DOX@RBCm efficiently inhibited CRC cells in vitro and demonstrated remarkable anti‐tumor effects in vivo, providing novel insights for nanomedicine optimization and deepening our understanding of the role of the Hippo/YAP1/SOX9 pathway in CRC development." (PMID 39523731, 2025). "Given the well-established role of YAP1 and Snail1 as tumor promoters, their stabilization could contribute to more aggressive tumor characteristics, including an increased cancer stem cell population, enhanced cell proliferation, and metastasis." (PMID 39827153, 2025). "We next investigated whether YAP1 target genes are involved in tumor‐promoting function of CDK4/6 in CRC." (PMID 39968498, 2025). "In contrast, other studies have suggested that cytoplasmic YAP1 may exert tumor-suppressive effects, especially in luminal subtypes." (PMID 40731926, 2025). "Emerging evidence suggests that PP1γ may regulate YAP1 activity by regulating its dephosphorylation, thus contributing to tumor invasion and metastasis." (PMID 40626009, 2025).